INS (insulin)
Diseases named in the same sentence as INS in open-access papers (continued):
Sharing a sentence is not in itself a finding about the gene and the disease.
Anxiety (continued). "High anxiety can lead to the release of sympathetic hormones, thereby increasing cortisol and glucose levels, reducing the insulin release, or affecting the sensitivity and resistance of insulin hormones." (PMID 35855329, 2022). "Expert patient education programmes for people with T1DM such as DESMOND16 and X‐PERT17 can go a long way to provide the necessary information to alleviate anxiety about ‘balancing the equation’ for diet, exercise and insulin dosing and to build confidence in self‐management." (PMID 34921531, 2022). "In HFD induced obese animals, resistance to metabolic hormonal signals, such as leptin and insulin may explain the corresponding increases in anxiety levels." (PMID 34064242, 2021). "Some participants used insulin and initially did not want to initiate insulin use because they needed to inject regularly, and this caused anxiety and fear about the pain and discomfort caused by the needle." (PMID 34616293, 2021). "Importantly, these studies suggest that ELS in combination with a WD prevents anxiety-like behavior despite leading to a compromised metabolic phenotype, as demonstrated by weight gain, adiposity, and elevated plasma insulin, leptin, and glucose levels." (PMID 33642988, 2021). "Based on the metabolite–gene network analysis, RIB induced depressive- and anxiety-like behavior and spatial memory impairment might be mediated by the insulin-POMC-MEK-TCF7L2 pathway." (PMID 33531473, 2021). "Patients treated with insulin 33/115 (28%) for less than one month had a high injection anxiety score on an author-created questionnaire, 16/115 (14%) of whom had avoided injections and 48/115 (42%) indicated they would be “troubled by more frequent injections”." (PMID 34111207, 2021). "This study will measure changes in intestinal flora, insulin resistance, blood glucose, blood lipids, BMI, waist to hip ratio, anxiety, and sleep status, providing a comprehensive understanding of psychological and physical changes before, during, and after each method and their maintenance." (PMID 32925754, 2020). "Poor sleep quality and anxiety both activate the hypothalamic-pituitary-adrenal axis, stimulating sympathetic nervous system-adrenal responses, increasing platelet aggregation and inflammation, decreasing insulin sensitivity, and worsening glycemic control." (PMID 32448338, 2020). "High anxiety can result in the release of sympathetic hormones that can elevate both cortisol and glucose levels, decrease insulin release, or affect the sensitivity and resistant of the insulin hormone." (PMID 31485387, 2019). "In conclusion, this study showed that CFD diet induced anxiety related activities, and impairment in spatial learning and memory which may related with insulin resistance." (PMID 30153273, 2018). "It is plausible that acupuncture may be a novel adjunctive treatment for weight loss that can both optimise behavioural change through reducing anxiety and appetite, as well as impacting on physiological markers such as leptin, ghrelin and insulin." (PMID 30409195, 2018). "Acupuncture may also improve insulin sensitivity and may further impact on weight by reducing anxiety." (PMID 30409195, 2018). "This would be congruent with our previous findings that insulin-induced phosphorylation of Kv1.3 and resultant decrease in channel open probability evokes a reduction in anxiety behaviors when intranasally administered to the OB." (PMID 29615878, 2018). "Patients who have started on insulin and demonstrated improved health outcomes may have passed through the same anxiety as those patients who have concerns and so may play beneficial roles in such programs." (PMID 28405339, 2017). "However, insulin treatment significantly alleviated anxiety in the APP/PS1 mice to a level comparable to wild‐type controls, as indicated by the increased percent of time spent in the center compared with APP/PS1‐veh mice." (PMID 27457264, 2016).
Anxiety (continued). "Insulin therapy is commonly associated with negative connotations and often causes dysfunctional emotions such as fear, anxiety." (PMID 24236071, 2013). "Conversely, some of the participants used glargine pre-study and, for those changing to a relatively untried basal insulin preparation, anxiety could have induced increased mental burden, reducing the magnitude of the advantages identified here." (PMID 22150786, 2012). "In addition, this preoperative fasting protocol has been associated with decreased organic response to trauma and inflammation and reduced insulin resistance while avoiding the undesired symptoms of thirst, hunger, anxiety, and malaise and limiting patient dissatisfaction." (PMID 40142917, 2025). "Consequently, some studies suggest that such exercises may improve NAFLD progression by alleviating stress and anxiety, improving insulin sensitivity and hepatic fat accumulation, and regulating hormone levels, including reducing cortisol." (PMID 39376897, 2024). "Consistent with these important roles of Akt1 in insulin signaling, our experiments demonstrate that activation of Akt1 with the small molecule SC79 increases viability of HEK293 cell expressing ND‐causing genes, and enhances long‐term memory and ameliorates dysregulated anxiety levels in AD mice." (PMID 37984409, 2023). "Levels of anxiety, eating behavior scores and physiological parameters (i.e., body weight, V̇O2peak, blood pressure, fasting glucose, blood lipids, and serum metabolic hormones including insulin, C-peptide, leptin, and ghrelin) were measured before and after the intervention." (PMID 35873416, 2022). "Finally, metabolite–gene network, qRT-PCR and western blot analysis showed that the insulin-POMC-MEK-TCF7L2 and MAPK-CREB-GRIN2A-CaMKII signaling pathways were respectively associated with RIB and MAN induced depressive/anxiety-like behavior and spatial memory impairment." (PMID 33531473, 2021). "This may explain the reduced insulin levels and the increased anxiety in AN individuals." (PMID 33652962, 2021). "In confounder-adjusted analyses, we found no strong evidence that prenatal anxiety was associated with trajectories of lean mass from 9 to 18 years; glucose from 7 to 18 years and insulin, triglyceride, HDL-c and non-HDL-c, all from birth to 18 years." (PMID 34911713, 2021). "Additionally, the pharmacological therapy with opioids, benzodiazepnics, and insulin for the treatment of physiological changes (pain, agitation, anxiety, and metabolic disorders) and to minimize external factors such as noise, often contribute to higher mortality rates in the ICU." (PMID 32802502, 2020). "When compared to animals only fed with a CAF diet, CAF withdrawal increased anxiety in the open field, slightly decreased body weight, and completely recovered the liver weight, insulin sensitivity and the standard levels of glucose, insulin and triglycerides in plasma." (PMID 24482678, 2014). "One hypothesis would be that insulin resistance in hippocampus might explain the enhanced anxiety." (PMID 24349472, 2013). "Furthermore, an approach of continuous feeding may avoid wide glucose and insulin excursions and minimize refeeding shifts as well as anxiety and nervousness." (PMID 23112917, 2012). "A United Kingdom study evaluating changes of quality of life for patients with GLP1-RA demonstrated that the therapy significantly reduced the Hospital Anxiety and Depression Scale (HADS) scores, compared with insulin-treated patients." (PMID 35281896, 2022). "Intranasal delivery of insulin in awake mice can transmit regulatory and metabolic hormones across the blood‐brain barrier (BBB), significantly improve memory and downgrade anxiety levels in rats." (PMID 32281722, 2020). "Anxiety is closely relevant with the dysregulation of the hypothalamic-pituitary-adrenal axis (HPA), which can trigger insulin resistance." (PMID 31396018, 2019).
Anxiety (continued). "Not being in control of their insulin or having access to key information about their meals led to upset and anxiety." (PMID 41358572, 2025). "Interestingly, insulin and Insulin-like Growth Factor (IGF-1) signaling in the amygdala has been shown to affect synaptic function and to influence anxiety-like behavior in mice." (PMID 40978196, 2025). "The result shows male offspring of 50 mg/kg-supplemented obese dams have comparable total fat (%), lipid profile, insulin level, FBG level, plasma insulin level, recognition index, low anxiety level, and improved hypothalamic FRAP and GSH levels to the normal group." (PMID 36986254, 2023). "Women in the GDM-insulin group had significantly higher levels of anxiety than the non-GDM group at both time points." (PMID 36733299, 2023). "GLP1-RA users that took metformin, sulfonylurea and oral medication combination had lower risk of anxiety, so as to those that did not use TZD, acarbose, SGLT2 inhibitors, DPP4 inhibitors, or insulin." (PMID 35281896, 2022). "Secondary outcomes include whole body and regional lean and adipose tissue mass; muscle strength and power; insulin sensitivity, lipids, and inflammatory markers; SCI functional index and wellbeing (mood, anxiety, pain, life satisfaction and depressive symptoms); and safety." (PMID 35614404, 2022). "Data from a large, community-based study showed that a group of patients who had severe depression and anxiety symptoms showed higher HbA1c levels and a greater need for insulin than those who showed no anxiety symptoms." (PMID 34646171, 2021). "On the HABS anxiety subscale, DDS emotional burden subscale, and DDS regimen-related distress subscale, all item scores as well as the mean subscale score were significantly lower while using IDeg than with the previous basal insulin (all P < 0.0001)." (PMID 33550540, 2021). "Needlestick injuries and injection pain can trigger anxiety and fear from insulin injection, leading to potential disadvantages, such as limited adherence to insulin therapy, suboptimal glycemic control, and negative impact on the quality of life." (PMID 33927957, 2021). "D12492 (rodent diet with 60 kcal% fat) has also been used in various studies showing that HFD leads to an increase in anxiety in the OFT, impairments in spatial memory, increases in blood glucose and insulin when paired together with stress, and sex differences with regards to behavioral testing." (PMID 33669543, 2021). "Among females, the BIPQ dimensions consequences, personalcontrol, treatment control, identity, coherence, emotional representations, andconcern, in addition to BMQ insulin concern, age, BMI, HAD anxiety anddepression, and the COPE subscales venting emotions and denial, were enteredinto the equation." (PMID 33282331, 2020). "The patient's symptoms of jerky myoclonus-like movement, abdominal stiffness with painful spasms, and muscle rigidity were exacerbated by sound, anxiety, and subcutaneous insulin injections, regardless of the treatment regimen (Insulatard or regular insulin)." (PMID 32982980, 2020). "We found that like the exposure to anesthesia with sevoflurane, insulin administration did not have any significant effect on spontaneous activity and anxiety, as determined by the OF test." (PMID 31354415, 2019). "Intranasal insulin delivery in mice for 7 days was shown to have anxiolytic properties in the light/dark box test, but insulin did not have any effect on anxiety behavior in the marble-burying test and elevated plus maze." (PMID 24109426, 2013). "One strength of this study is that in addition to negative appraisal of insulin treatment, a broad assessment of more generic psychological variables such as well-being, diabetes-related distress, anxiety, and depressive symptoms were longitudinally assessed." (PMID 20920319, 2010).
Anxiety (continued). "Preoperative carbohydrate solutions are known to reduce insulin resistance by ≤50%, prevent muscle breakdown, decrease hospital LOS, reduce time to recovery, and improve postoperative function while simultaneously decreasing patient-reported preoperative thirst, hunger, and anxiety." (PMID 39617150, 2025). "Although no direct relationship is observed between stress and anxiety with metabolic markers such as insulin or blood pressure, these factors could be areas of concern that require further research." (PMID 39275240, 2024). "Contrary to our hypothesis, anxiety in women with GDM treated with insulin did not attenuate over the course of pregnancy." (PMID 36733299, 2023). "If insulin treatment leads to confrontation with anxiety (in anxiety disorder) or circumstances similar to or related to the trauma (in PTSD triggered by medical trauma), the insulin treatment could be more likely to be avoided in these patients than in CAYA without mental disorders." (PMID 36707607, 2023). "Regarding psychological wellbeing, women with GDM treated with insulin reported significantly higher levels of anxiety at both time points compared with women in the non-GDM group (median STAI-6 score 12.0 vs 8.0, P = 0.005 at 24–34 weeks gestation; 12.0 vs 7.5, P = 0.046 (at ∼36 weeks gestation))." (PMID 36733299, 2023). "Results from hTau mice demonstrate that the presence of a non-mutant WT human tau triggers insulin resistance, elicit impairments in spatial learning and object recognition memory, and does not restore anxiety, memory and metabolic alterations in mice lacking endogenous murine tau." (PMID 32226410, 2020). "This regimen does not modify peripheral levels of insulin or glucose, but it increases phosphorylation of IR kinase and Kv1.3 channel in the olfactory bulb and it enhances olfactory discrimination, among other behavioral phenotypes including anxiety and memory." (PMID 21966386, 2011). "In women with GDM treated with diet, anxiety scores were higher than those of the women without GDM, but lower than those of women treated with insulin at both time points." (PMID 36733299, 2023). "Despite the defects in insulin and leptin release during CORT treatment, Caps2 KO mice did not exhibit heightened anxiety/depressive behavior compared with WT mice." (PMID 25754523, 2015). "As the horses in the present study showed no signs of anxiety and were accustomed to blood pressure recordings it is reasonable to assume that the decrease seen in blood pressure at the end of the EHC is the result of insulin induced vasodilation." (PMID 27766986, 2016).
dementia (362 papers, 2009 to 2026). Loss of intellectual abilities interfering with an individual's social and occupational functions. "Among these, failure in energy metabolism due to insulin resistance within the brain is known as one of the major initial causes of dementia." (PMID 40720390, 2025). "Strategies aimed at reducing glucose levels can positively influence cognition in the elderly population, emphasizing their importance in prevention, as anything promoting insulin resistance ultimately increases the risk of dementia." (PMID 40806031, 2025). "Although the causal link between T2DM and dementia remains debated, these conditions contribute to vascular dysfunction, neuroinflammation, and insulin resistance—mechanisms implicated in dementia pathogenesis." (PMID 40717728, 2025). "Disrupted insulin signaling makes neurons vulnerable to metabolic stress, leading to neuronal dysfunction, decreased cognitive ability, and an increased risk of dementia." (PMID 41470817, 2025). "Conversely, rodents administered streptozotocin combined with high-fat diets are animal models with abnormal brain energy metabolism and insulin resistance which is considered an important factor causing sporadic dementia." (PMID 40720390, 2025). "A comparative study involving metformin, DPP4i, GLP1 analogs, SU, and insulin found that all combinations, except those including SU, were associated with lower odds ratios for developing dementia." (PMID 41146261, 2025). "Two extremes of insulin distribution (lowest and highest 15th percentile) had an increased risk for dementia." (PMID 38708587, 2024). "These disorders share some pathological commonalities, such as insulin signalling abnormalities which has taken a predominant stance as a risk factor for developing dementia, both in AD and T2DM patients." (PMID 39170185, 2024). "Dysregulation of inflammasome signaling is implicated in the pathogenesis metabolic dysfunction and dementia, both of which are characterized by chronic inflammation, impaired glucose metabolism, and disrupted insulin signaling." (PMID 38840215, 2024). "In some studies, metformin and sulphonylureas have been associated with reduced dementia risk, while in other studies, metformin, insulin treatment, and glitazone have been linked to increased cognitive symptoms and dementia risk." (PMID 38467963, 2024). "By examining postmortem brain tissues, previous studies have consistently found insulin signaling abnormalities in patients with Alzheimer’s disease (AD), a leading cause of dementia in older adults." (PMID 38029396, 2024). "The developing knowledge of the brain's responsiveness to insulin has provided insight into the possible connection between the disorders associated with insulin and dementia." (PMID 39493064, 2024). "Lastly, insulin therapy only showed an association with a decrease in the incidence of dementia in patients using combined insulin therapy." (PMID 38152822, 2023). "We previously observed a U-shaped association between fasting insulin in middle-aged women and dementia up to 34 years later." (PMID 37420130, 2023). "This cohort study investigates the association of metformin therapy cessation with dementia incidence and mediation of this association by hemoglobin A1c level and insulin use." (PMID 37878309, 2023). "This makes sense as some studies have found that using insulin increases the risk of dementia, increasing up to 3x the odds." (PMID 38152822, 2023). "Insulin restores cerebral glucose, which is the main nutrient for brain neurons whose depletion is responsible for the dementia; and edaravone decreases ROS, which are intrinsic causes of neuropathology in AD." (PMID 37176592, 2023). "Numerous studies related to insulin/insulin-like growth factor 1 (IGF-1) signaling are linked with various types of dementia." (PMID 37511207, 2023).